DEPDC1 (DEP domain containing 1)
Diseases named in the same sentence as DEPDC1 in open-access papers (continued):
Sharing a sentence is not in itself a finding about the gene and the disease.
liposarcoma (continued). "We measured the expression levels of DEPDC1 and KIF20A in clinical liposarcoma tissues at mRNA and protein levels." (PMID 40600015, 2025). "Here, our findings revealed that the expression levels of DEPDC1 and KIF20A were elevated in liposarcoma compared to the paired adjacent adipose tissues, with their expression positively correlating with the malignancy of liposarcoma." (PMID 40600015, 2025). "In conclusion, this study suggested that DEPDC1 might interact with KIF20A to promote the occurrence and progression of liposarcoma by activating PI3K/AKT/mTOR signaling pathway." (PMID 40600015, 2025). "In conclusion, the expression of DEPDC1 and KIF20A was elevated in liposarcoma." (PMID 40600015, 2025). "Moreover, the overexpression of DEPDC1, coupled with the simultaneous knockdown of KIF20A in liposarcoma cells, partially inhibited the progression in malignant phenotypes of these cells and the activation of PI3K/AKT/mTOR signaling pathway compared to the control groups." (PMID 40600015, 2025).
psoriasis (1 paper, 2023). An autoimmune condition characterized by red, well-delineated plaques with silvery scales that are usually on the extensor surfaces and scalp. "In our study, PTG1, HMMR, PBK, FEN1, DEPDC1 may be some psoriasis-related genes in IL-17A treating of psoriasis." (PMID 37029373, 2023).
sarcoma (1 paper, 2025). A usually aggressive malignant neoplasm of the soft tissue or bone. "High DEPDC1 expression was significantly associated with shorter disease-free survival (DFS) in sarcoma patients." (PMID 40600015, 2025). "Furthermore, the Kaplan-Meier (KM) online platform indicated that patients with elevated DEPDC1 expression in sarcomas were significantly associated with a poor prognosis." (PMID 40600015, 2025). "The GEPIA online tool indicated that DEPDC1 expression was linked to patients’ survival in sarcoma." (PMID 40600015, 2025). "In this study, the expression and clinical relevance of DEPDC1 in sarcoma was assessed by employing data from The Cancer Genome Atlas (TCGA) data and conducting Kaplan-Meier online analyses, respectively." (PMID 40600015, 2025). "Since the TCGA database did not distinguish between sarcoma subtypes, we analyzed the expression level of DEPDC1 across sarcomas and its correlation with patients prognosis." (PMID 40600015, 2025). "The GEPIA website indicated a positive correlation between KIF20A and DEPDC1 expression in sarcoma." (PMID 40600015, 2025). "Kaplan–Meier (KM) curves further demonstrated that high DEPDC1 expression correlated with reduced overall survival (OS) and DFS in patients with sarcoma." (PMID 40600015, 2025).
uterine tumours (1 paper, 2018). "To further confirm whether PTEN mutated tumours restored HR repair deficiency, we investigated the relationship between PTEN mutation and HR-related genes (HR signature, TTK and DEPDC1) in colon and uterine tumours including non-hypermutators." (PMID 29880869, 2018).
cancer (44 papers, 2012 to 2025). A tumor composed of atypical neoplastic, often pleomorphic cells that invade other tissues. "Future studies are necessary to validate the diagnostic and prognostic implications of DEPDC1, enabling the development of targeted therapeutic interventions targeting this protein, which holds promise for enhancing treatment efficacy in cancer patients." (PMID 41057958, 2025). "DEPDC1 is a newly identified cancer-associated gene that is part of a transcription repressor complex and related to cellular processes such as the cell cycle, transcription, mitosis and apoptosis." (PMID 36768316, 2023). "FOXM1 interacts with DEPDC1, which causes cancer in OSCC cells, according to these fundamental in vitro data." (PMID 36072787, 2022). "DEPDC1 is thought to be a novel diagnostic marker for human cancers and a molecular-target for novel therapeutic drugs or cancer peptide-vaccine." (PMID 34268303, 2021). "DEP domain containing 1 (DEPDC1) is a novel tumor-associated gene, which is aberrantly expressed in multiple types of cancer and involves in tumorigenesis and cancer progression." (PMID 31032225, 2019). "Notably, DEP domain-containing protein 1 A (DEPDC1A), also known as DEPDC1, has been closely associated with the development and prognosis of human cancers." (PMID 38717641, 2024). "According to our results, DEPDC1 was remarkably upregulated in the tissues of NSCLC patients compared with non-carcinoma tissues, linked with gender, stage, T classification and N classification based on TCGA data and associated with smoking status and stage according to GEO datasets." (PMID 38564630, 2024). "Meanwhile, DEPDC1 was reported to be relevant to various cancer associated pathways." (PMID 36768316, 2023). "In addition, DEPDC1 is known to be associated with various biological processes of other cancers." (PMID 36768316, 2023). "CONCLUSIONS: These findings underscore the potential of DEPDC1 as a crucial biomarker in cancer prognosis and the biologic pathways modulation." (PMID 41057958, 2025). "The role of DEPDC1 in promoting cancer development had been increasingly recognized, and it is widely regarded as a putative oncogene." (PMID 40600015, 2025). "Currently, the role of DEPDC1 in promoting cancer development has been progressively unveiled, and it is widely regarded as a potential oncogene." (PMID 40600015, 2025). "DEPDC1 is involved in cell cycle progression and promotes cancer cell survival by inhibiting apoptosis." (PMID 39596419, 2024). "Pan-cancer analysis using TIMER2.0 online tool found that DEPDC1 was highly expressed in NSCLC tissues, consistent with prior findings." (PMID 38564630, 2024). "Another study reported that the activation of the Wnt/β-catenin signaling pathway by DEPDC1 promotes the proliferation and metastasis of cancer." (PMID 38929279, 2024). "The analyses of the LUSC groups alone revealed that DEPDC1 was upregulated in cancer tissues (P < 0.001)." (PMID 38564630, 2024). "Afterwards, for exploring the effect of DEPDC1 on cancer cells, DEPDC1 was silenced in NCI-H1299 cells." (PMID 38564630, 2024). "DEPDC1 expression was significantly up-regulated in LUAD compared with non-carcinoma tissues (P < 0.001)." (PMID 38564630, 2024). "Several signaling pathways were linked to the regulation of proliferation (Wnt/β-catenin signaling and Pi3K/AKT-signaling) and apoptosis (NF-κB and DEPDC1-caspase signaling) by PCDHs in cancer." (PMID 37098643, 2023). "Together, the results suggest that DEPDC1 mediates a cancer-inducing function in OSCC cells in addition to facilitating OSCC progression through modulating the OSS cell growth environment." (PMID 36072787, 2022). "The results from gene enrichment examination suggest that general and WNT/β-catenin-specific cancer signaling pathways related to HCC cancer genes had a positive correlation with DEPDC1 expression." (PMID 36072787, 2022). "Together, these results showed that in OSCC, DEPDC1 plays a cancer-inducing role in vivo and in vitro." (PMID 36072787, 2022).
cancer (continued). "DEPDC1 has since been discovered to play a role in cancer progression and is widely regarded as a possible oncogene." (PMID 36072787, 2022). "Previous reports have demonstrated that DEPDC1 promotes cell proliferation, invasion, and angiogenesis in numerous cancers regulated by multiple signaling pathways." (PMID 34268303, 2021). "Studies have shown that high DEPDC1 expression is an independent predictor of cancer-related death and recurrence." (PMID 34539726, 2021). "More importantly, recent studies showed that DEP domain containing 1A (DEPDC1A), alias DEPDC1, was tightly correlated with the development and prognosis of several types of human cancers." (PMID 34210956, 2021). "DEPDC1 overexpression has been found negatively correlated with the prognosis of many malignant tumors." (PMID 33140894, 2020). "GSCAlite algorithm analysis revealed that the expression and overall survivals across diverse cancer types of DEPDC1 were more obvious than other genes." (PMID 32396871, 2020). "The SNV frequency across cancers analyzed by GSCAlite algorithm also revealed that DEPDC1 had the most significant changes." (PMID 32396871, 2020). "Several studies showed that the DEP domain containing 1 (DEPDC1) protein was a novel oncoantigen that was aberrantly overexpressed in multiple types of cancers." (PMID 32149111, 2020). "Currently, DEPDC1 promoting cancer development was gradually discovered and had been widely considered as a putative oncogene." (PMID 31032225, 2019). "It has been shown that knockdown of endogenous DEPDC1 expression by siRNA resulted in significantly growth suppression in these cancer cell lines." (PMID 28969015, 2017). "To date, several studies have shown that DEPDC1 is aberrantly overexpressed in several types of cancers suggesting its therapeutic potential in cancers." (PMID 28969015, 2017). "DEPDC1 is not only an important target for cancer biology research, but also provides potential clinical application prospects for early diagnosis and targeted treatment of cancer." (PMID 40018408, 2025). "The function of DEPDC1 is still under investigation, but existing studies have shown that it plays an important role in the occurrence, development, and metastasis of various cancers." (PMID 40018408, 2025). "Additionally, the UALCAN database revealed that high DEPDC1 expression correlated with nodal metastasis, high tumor grade, and advanced cancer stage in KIRC patients." (PMID 39068164, 2024). "DEP domain containing 1 (DEPDC1) is an important modulator of the Wnt pathway, reported as a tumor-related gene that promotes carcinogenesis and is found to be upregulated in numerous cancer types." (PMID 38929279, 2024). "In addition, other studies have shown that DEPDC1 aids cancer development and growth in lung adenocarcinoma, gastric cancer, oral squamous cell carcinoma, colorectal cancer, liver cancer and breast cancer." (PMID 38929279, 2024). "In this respect, it has been shown that DEPDC1 shows remarkable up-regulation within cancer samples in comparison with corresponding non-carcinoma samples, which is negatively related to dendritic cells during immune infiltration analysis in esophageal squamous cell carcinoma." (PMID 38564630, 2024). "Recently, DEPDC1 was identified as participating in tumorigenesis and cancer progression." (PMID 36768316, 2023). "It was recently reported that DEPDC1 is mainly found in cancer cell nuclei." (PMID 36072787, 2022). "In OSCC cancer cells, correlations between DEPDC1 and FOXM1 were also discovered." (PMID 36072787, 2022). "Elevated DEPDC1 expression within cancer cell lines and human OSCC has been identified." (PMID 36072787, 2022). "Furthermore, this study describes a novel regulatory signaling pathway driven by DEPDC1 that enhances cancer characteristics by leveraging the Wnt/β-catenin OSCC." (PMID 36072787, 2022).
cancer (continued). "In addition to correlation with poor prognosis of cancer, numerous studies also explored the biological roles and regulatory mechanisms of DEPDC1 in different malignant tumors." (PMID 33140894, 2020). "There are several reports investigated DEPDC1's role in tumorigenesis of other cancers." (PMID 33021072, 2020). "Since increased cellular proliferation, migration and invasion are hallmarks of cancer cells, our observation that DEPDC1 knockdown impairs proliferation, migration and invasion of A549 cells provides cellular evidence to address how DEPDC1 negatively affects LUAD patients' prognosis." (PMID 33021072, 2020). "DEP domain containing 1(DEPDC1) is involved in the tumorigenesis of a variety of cancers." (PMID 33021072, 2020). "As up-regulation of DEPDC1 mRNA has been observed in NPC as well as other cancers, it is highly likely that DEPDC1 could be also aberrantly up-regulated at transcriptional level in cancers." (PMID 28969015, 2017). "Several studies suggested that overexpression of DEPDC1 in cancers might be regulated through multiple molecular mechanisms." (PMID 28969015, 2017). "Given the well-known close relationship between cell cycle dysregulation and tumorigenesis, DEPDC1 might be widely involved in the development of many types of cancers." (PMID 28969015, 2017). "However, it remains unclear whether DEPDC1 is the main mechanism for promoting the proliferation and migration of malignant tumors." (PMID 36479633, 2023). "Moreover, high DEPDC1 expression was also shown in advanced stage cancer and lymph nodes metastasis, suggesting that DEPDC1 might be an advanced biomarker in OSCC." (PMID 36768316, 2023). "Whether there is connection between DEPDC1 and autophagy in cancer cells remains unknown." (PMID 33021072, 2020). "DEP domain containing 1 (DEPDC1) has been well-known as a significant contributor to tumorigenesis and cancer progression." (PMID 40600015, 2025). "The S-588410 comprises five HLA-A*24:02-restricted peptides from cancer-testis antigens (URLC10, CDCA1, KOC1, DEPDC1, and MPHOSPH1)." (PMID 38990441, 2024). "DEPDC1, DEP (disheveled, EGL-10, pleckstrin) domain-containing 1 protein, is a novel oncoantigen upregulated in multiple types of cancers, including HCC." (PMID 34268303, 2021). "Thus, further studies are needed to investigate whether rational combination of DEPDC1 siRNA or inhibitors with the IKK/NF-κB inhibitors or chemotherapeutic agents will achieve a synergistic antitumor effect in NPC as well as other types of cancers." (PMID 28969015, 2017). "Accumulating evidence demonstrates that DEPDC1 is significantly upregulated in tumor tissues than in non-malignant tissues across 31 cancer types." (PMID 41057958, 2025). "They found that miR-130b-3p inhibits DEPDC1 expression, which, via the TGF-β signalling pathway, leads to reduced proliferation, migration, and apoptosis suppression in cancer cells; additionally, a decrease in serum exosomal miR-130b-3p was noted in NSCLC patients." (PMID 39682592, 2024). "The DEPDC1 (DEP domain-containing 1) protein is a highly conserved protein not expressed in normal human tissues, except in the testis, but it is aberrantly expressed in many cancers." (PMID 34684876, 2021). "Furthermore, UALCAN program analysis using TCGA data suggested that DEPDC1 was elevated across stage 1 to 4 of NSCLC tumor samples, and DEPDC1 was up-regulated in most cancer types." (PMID 32396871, 2020).
cancer (continued). "Indeed, we have examined several peptides derived from a variety of cancer-testis antigens that have the oncogenic activity, including KIF20A, DEPDC1, MPHOSPH1, URLC10(LY6K),TTK, KOC1(IMP3), CDCA1, RNF43, and TOMM34." (PMID 24237633, 2013).
tumor (39 papers, 2013 to 2025). "As a result, the glycolysis-related biomarker DEP domain containing 1 (DEPDC1), which is a part of a transcription repressor complex and a newly discovered tumor-associated gene, was identified as being associated with the prognosis of OSCC." (PMID 36768316, 2023). "DEPDC1, located on 1p31.3, was a newly discovered novel tumor-associated gene and highly conserved from Caenorhabditis elegans to human." (PMID 32396871, 2020). "Its expression was significantly associated with tumor malignancy and advanced stage, and the high DEPDC1 level was obviously correlated with poor clinical outcome." (PMID 31032225, 2019). "Of note, knockdown of DEPDC1 in CNE-1 stable cell lines caused an obvious decrease in tumor weight and volume compared with the control group." (PMID 28969015, 2017). "Furthermore, the high expression of DEPDC1 in tumor tissues was linked to tumor progression and poor prognosis." (PMID 40600015, 2025). "Based on GEO database analysis, DEPDC1 was associated with smoking status and tumor stage." (PMID 38564630, 2024). "The high expression of DEPDC1 in non-tumor liver is an independent risk factor for late relapse." (PMID 34539726, 2021). "We have for the first time found that DEPDC1 is highly expressed in NPC tissues relative to non-tumor tissues, and knockdown of DEPDC1 caused significant growth suppression of NPC cells in vitro and in vivo, and also inhibited cell migration and invasion in NPC cells." (PMID 28969015, 2017). "Moreover, in vivo study demonstrated that DEPDC1 knockdown also caused significant inhibition of tumor growth in the NPC xenograft nude mouse model." (PMID 28969015, 2017). "DEP Domain Containing 1 (DEPDC1) and Maternal Embryonic Leucine Zipper Kinase (MELK) are directly associated with oncogenesis and tumor progression." (PMID 39596419, 2024). "This work also explored the relations among tumor immune microenvironment, immune cell infiltration, immunotherapeutic targets and DEPDC1 level." (PMID 38564630, 2024). "Timer 2.0 database analysis revealed that DEPDC1 was expressed at higher levels in tumor tissues compared to normal tissues, particularly in KIRC." (PMID 39068164, 2024). "Quantitative analysis of the TMA2021 cohort using H-score revealed higher DEPDC1 expression in tumor tissues compared to para-cancerous tissues." (PMID 39068164, 2024). "We then constructed a nude mouse subcutaneous tumor model using A498 cells (Vector and OE-DEPDC1) to explore the effect of overexpressing DEPDC1 on RCC cell growth in vivo." (PMID 39068164, 2024). "IHC staining revealed higher expression of DEPDC1 in the tumor cell nucleus of the OE-DEPDC1 group than that in the Vector group." (PMID 39068164, 2024). "In summary, these results show that DEPDC1 promoted the proliferation, migration, invasion and subcutaneous tumor formation ability of RCC cells." (PMID 39068164, 2024). "The protein expression levels of DEPDC1 appeared significantly higher in the advanced tumor, node, metastasis (TNM) stage group, and the lymphatic metastasis‐positive group." (PMID 36479633, 2023). "Analysis of DEPDC1 expressions in human tumour tissues from the UALCAN database indicated that SSRP1 is upregulated in several tumour tissues." (PMID 36072787, 2022). "In contrast, increased in vivo tumour size was observed following the overexpression of DEPDC1 in CAL-27 tumours (right)." (PMID 36072787, 2022). "We suppressed FOXM1 endogenous expression in CAL–27 cells overexpressing DEPDC1 to see if DEPDC1-mediated FOXM1 regulation promotes tumour growth." (PMID 36072787, 2022). "Because DEPDC1 expression increased in CRC tumor tissues and previous study has demonstrated that high expression of DEPDC1 was related to the poor tumor node metastasis (TNM) stage and recurrence." (PMID 35582195, 2022). "We next investigated the impact of DEPDC1 on nude mouse tumour growth to obtain confirmation that DEPDC1 enhanced tumour progression and found that DEPDC1 knockdown shrank the tumours (left)." (PMID 36072787, 2022).